CDK13 (cyclin dependent kinase 13)
Diseases named in the same sentence as CDK13 in open-access papers (continued):
Sharing a sentence is not in itself a finding about the gene and the disease.
thyroid cancer (4 papers, 2021 to 2023). "To examine the function of CDK13 and how its expression affects the main cancer hallmarks in thyroid cancer, we performed loss-of-function assays using three independent siRNAs that markedly decreased CDK13 RNA and protein levels in Cal62 and TPC1 thyroid cancer cells." (PMID 34496885, 2021). "Notably, CDK13 knockdown suppressed cell invasion, a fundamental hallmark for cancer progression and dissemination, pointing to an oncogenic role for CDK13 in thyroid cancer cells." (PMID 34496885, 2021). "Otherwise, Cyclin-dependent serine/threonine protein kinase 13 (CDK13) is required for constitutive and alternative pre-mRNA splicing in thyroid cancer." (PMID 37853437, 2023). "Fifth, editing of CDK13 increased its protein abundance and promoted cancer cell hallmarks in thyroid cancer." (PMID 35406793, 2022). "This work opens the door for detailed studies of the mechanism of action of CDK13 in thyroid cancer with respect to how edited CDK13 triggers the observed oncogenic behavior." (PMID 34496885, 2021). "We observed that WT-CDK13 correlated highly with the nuclear speckles in thyroid cancer cells, suggesting that the described role of CDK13 in splicing is maintained in thyroid cells." (PMID 34496885, 2021). "This indicates that the outcomes are independent of the endogenous CDK13 WT/edited levels, and suggests that CDK13 editing has a relevant role in the oncogenic function of ADAR1 in thyroid cancer." (PMID 34496885, 2021). "To assess the importance of the CDK13 editing event in the oncogenic function of ADAR1 we overexpressed the edited form of CDK13 in thyroid cancer cells that were simultaneously silenced for ADAR1 using two different siRNAs." (PMID 34496885, 2021). "We further investigated CDK13 because of its oncogenic behavior in thyroid cancer cell lines and because an edited form of its transcript is dominant in primary thyroid tumors." (PMID 34496885, 2021). "Our functional analysis shows that, in accordance with previous studies, CDK13 acts an oncogene in thyroid cancer cells, identifying it as a new therapeutic target in thyroid and other cancer types." (PMID 34496885, 2021). "We report an oncogenic function for CDK13 in thyroid cancer and identify a new ADAR1-dependent RNA editing event that occurs in the coding region of its transcript." (PMID 34496885, 2021). "For example, ADAR can promote the development of thyroid cancer through RNA editing of CDK13." (PMID 37414093, 2023). "In summary, our work confirms ADAR1 as an oncogene in thyroid cancer and offers evidence of its mechanism of action through editing CDK13, which confers stronger tumorigenic properties to cells and delocalizes CDK13 from nuclear speckles, the main hub for splicing factors." (PMID 34496885, 2021). "There are few studies on the role of CDK13 in cancer and, to our knowledge, none of them have addressed its role in thyroid cancer." (PMID 34496885, 2021). "Overall, our data point to an oncogenic role for CDK13 in thyroid cancer, as the ADAR1-dependent editing of CDK13 provides an advantage for cancer progression and may explain the global change in splicing pattern observed upon ADAR1 knockdown." (PMID 34496885, 2021).
colorectal cancer (3 papers, 2012 to 2025). A primary or metastatic malignant neoplasm that affects the colon or rectum. "As also shown in TNBC cells, CDK13 positively regulates the translation of MYC, which is functionally relevant for the viability and proliferation of colorectal cancer cells downstream of CDK13." (PMID 39533070, 2025).
leukemia (3 papers, 2021 to 2024). A malignant (clonal) hematologic disorder, involving hematopoietic stem cells and characterized by the presence of primitive or atypical myeloid or lymphoid cells in the bone marrow and the blood. "Probably leukemia was a coincidental finding in this boy with CDK13-related disorder, but the case herein suggests that individuals with CDK13-related disorder also face risk of developing cancers." (PMID 35651941, 2022).
medulloblastoma (3 papers, 2021 to 2025). A malignant, invasive embryonal neoplasm arising from the cerebellum. "THZ1 inhibits CDK7, CDK12, and CDK13 and was described as radiosensitizer in a study on medulloblastomas." (PMID 34063457, 2021).
Cognitive impairment (2 papers, 2023 to 2025). Abnormal cognition is characterized by deficits in thinking, reasoning, or remembering. "Similar to UPS9X, disruption of CDK13 is associated with syndromic cognitive impairment." (PMID 37895297, 2023).
diabetes (2 papers, 2021 to 2025). "We report a homozygous variant in CDK13 and suggest that this gene causes an autosomal recessive disorder with hearing impairment, bicuspid aortic valve, diabetes mellitus and insipidus, clinodactyly, and gastrointestinal tract abnormalities." (PMID 33879837, 2021). "Of note is that the phenotype reported in the consanguineous family is that of Wolfram Syndrome (diabetes insipidus and diabetes mellitus with optical atrophy, and deafness, DIDMOAD), which is quite distinct from the phenotype of CDK13‐related disorder described so far." (PMID 39556044, 2025). "Whilst it is possible that the onset of diabetes and deafness might have not yet developed in the young individuals with CDK13‐related disorder, it is perhaps more likely that this is a distinct syndrome because of a different mechanism of action." (PMID 39556044, 2025).
gastric cancer (2 papers, 2021 to 2023). A primary or metastatic malignant neoplasm involving the stomach. "HMGA2 and CDK13 are coexpressed in gastric cancer, and higher expression of both these genes has been associated with poor prognosis." (PMID 36769170, 2023). "HMGA2 is an oncogene that promotes gastric cancer through a progression of S-G2/M transitions and targets CDK13." (PMID 36769170, 2023).
influenza (2 papers, 2013 to 2015). An acute viral infection of the respiratory tract, occurring in isolated cases, in epidemics, or in pandemics; it is caused by serologically different strains of viruses (influenzaviruses) designated A, B, and C, has a 3-day incubation period, and usually lasts for 3 to 10 days. "In addition to the PI3K pathway, the novel link to general viral regulator gene (CDK13) and a specific influenza T cell gene using transcriptomics (KLRG1) demonstrate the utility of our proposed framework." (PMID 25685197, 2015).
Kabuki syndrome (2 papers, 2017 to 2022). Kabuki syndrome (KS) is a multiple congenital anomaly syndrome characterized by typical facial features, skeletal anomalies, mild to moderate intellectual disability and postnatal growth deficiency. "Given the clinical feature overlap, CDK13 genotyping should be considered in individuals clinically suspected to have Kabuki syndrome but who lack molecular confirmation." (PMID 28807008, 2017).
lung adenocarcinoma (2 papers, 2013 to 2024). A carcinoma that arises from the lung and is characterized by the presence of malignant glandular epithelial cells. "CDK13, BMP1, RNF13, MAT2A, CHRNA4 are also among the genes in Merged-module whose over-expression has been reported in different cancers, however, their over-expression has been demonstrated in lung adenocarcinoma in this study." (PMID 23874428, 2013).
thyroid tumor (2 papers, 2021 to 2024). A benign or malignant neoplasm affecting the thyroid gland. "CDK13 was recently identified with editing sites at Q103R in thyroid tumors." (PMID 38835016, 2024). "Thus, the CDK13 c.308A > G editing event is present in thyroid tumor cells and is dependent on ADAR1 expression." (PMID 34496885, 2021).
triple-negative breast carcinoma (2 papers, 2021). An invasive breast carcinoma which is negative for expression of estrogen receptor (ER), progesterone receptor (PR), and human epidermal growth factor receptor 2 (HER2). "We believe that this is particularly relevant as ADAR1 and CDK13 have both been described as important factors and possible therapeutic targets in triple-negative breast cancer." (PMID 34496885, 2021). "However, a highly selective inhibitor of CDK13 that can disables triple-negative breast cancer cells progression and metastases." (PMID 33390186, 2021).
Wolfram-like syndrome (2 papers, 2021 to 2024). Wolfram-like syndrome is a rare endocrine disease characterized by the triad of adult-onset diabetes mellitus, progressive hearing loss (usually presenting in the first decade of life and principally of low to moderate frequencies), and/or juvenile-onset optic atrophy. "We performed whole-exome sequencing and identified a homozygous missense variant in CDK13 that segregates with a Wolfram-like syndrome in a consanguineous Pakistani family." (PMID 33879837, 2021). "Finally, Wolfram-like syndrome due to the CDK13 variant segregating in a Pakistani family was associated with a bicuspid aortic valve and cardiac arrest in one case." (PMID 38542026, 2024). "The identification of additional families with AR Wolfram-like syndrome due to CDK13 will aid in determining the complete disease spectrum and also serve to confirm the role of CDK13 in the etiology of AR Wolfram-like syndrome." (PMID 33879837, 2021).
Alzheimer disease (1 paper, 2019). A progressive, neurodegenerative disease characterized by loss of function and death of nerve cells in several areas of the brain leading to loss of cognitive function such as memory and language. "Recently, CDK13 was found remarkably dysregulated in hippocampus and suggested as one of the hub genes useful to elucidate Alzheimer’s disease." (PMID 31440507, 2019).
benign prostatic hyperplasia (1 paper, 2021). A non-cancerous nodular enlargement of the prostate gland. "To evaluate the potential role of CDK13 in the development of human PCa, we first examined the CDK13 mRNA expression in 30 PCa tissues and benign prostatic hyperplasia (BPH) by using RT-qPCR." (PMID 33390186, 2021).
Blepharophimosis (1 paper, 2018). A fixed reduction in the vertical distance between the upper and lower eyelids with short palpebral fissures. "Identification of CDK13 mutations in our cohort adds a further molecular cause of phenotypes within this spectrum, and therefore should be considered in the differential diagnosis of unresolved cases with Ohdo, Ohdo-like or blepharophimosis-ID syndromes." (PMID 29021403, 2018).
chordoma (1 paper, 2022). Chordomas are rare malignant tumors arising from embryonic remnants of the notochord in axial skeleton. "CDK inhibitors such as THZ1, NVP-2 and THZ531 that inhibit CDK7, CDK9, CDK12 and CDK13, respectively, have been shown to downregulate SE-related oncogene expression and promote DNA damage response gene loss in chordoma and acute T-lymphoblastic leukaemia cells, respectively." (PMID 35514959, 2022).
clear cell renal carcinoma (1 paper, 2026). A malignant epithelial neoplasm of the kidney characterized by the presence of lipid-containing clear cells within a vascular network. "Cyclin-dependent kinase 13 (CDK13) has emerged as a critical regulator of oncogenic metabolism, but its role in rewiring lipid metabolism in clear cell renal cell carcinoma (ccRCC) remains undefined." (PMID 41680470, 2026).
colon cancer (1 paper, 2012). "Of these, the following four genes were common to both HCC and colon cancer: CENPF, GMNN, CDK13, and FAM82B." (PMID 22912832, 2012).
cystic hygroma (1 paper, 2023). A benign lymphatic neoplasm usually arising from the neck and characterized by cystic dilation of the lymphatic vessels. "Detection of cystic hygroma with thickened nuchal fold led to prenatal genetic investigation, which identified a novel de novo likely pathogenic variant in the CDK13 gene (c.900C > G, p.Tyr300∗)." (PMID 37351084, 2023).
diffuse large B-cell lymphoma (1 paper, 2024). "On the other hand, CCNK is complexed with kinase CDK12 and CDK13, which are strongly associated with BRCA, AML and diffuse large B-cell lymphoma (DLBCL)." (PMID 38459430, 2024).
embryonic carcinoma (1 paper, 2019). "When neuronal differentiation model of mouse embryonic carcinoma cell (P19) was employed, CDK12 and CDK13 kinases participated in the axonal elongation through a common signaling pathway that modulates protein expression of CDK5." (PMID 31440507, 2019).
heart failure (1 paper, 2019). Inability of the heart to pump blood at an adequate rate to meet tissue metabolic requirements. "Animals with hypomorphic allele (Cdk13tm1a) retained low residual expression of CDK13 and they were lethal by E16.5 most due to heart failure and delayed development of several organs was caused likely due to insufficient supply of oxygen and nutrients." (PMID 31440507, 2019).
lymphoma (1 paper, 2025). A malignant (clonal) proliferation of B- lymphocytes or T- lymphocytes which involves the lymph nodes, bone marrow and/or extranodal sites. "nTA can then instead be used to infer putative regulators, such as CDK13, which can aid in understanding how lymphoma may form due to AICDA off-target mutations." (PMID 39878215, 2025).
myeloproliferative neoplasm (1 paper, 2026). A clonal hematopoietic stem cell disorder, characterized by proliferation in the bone marrow of one or more of the myeloid (i.e., granulocytic, erythroid, megakaryocytic, and mast cell) lineages. "Elevated CDK13 expression has been reported in myelodysplastic/myeloproliferative neoplasm with ring sideroblasts and thrombocytosis (MDS/MPN-RS-T), in which 80–90% of patients harbor SF3B1 mutations, a splicing factor regulated by CDK12/13." (PMID 41491919, 2026).
myocardial infarction (1 paper, 2019). Gross necrosis of the myocardium, as a result of interruption of the blood supply to the area, as in coronary thrombosis. "Interestingly, several miRNAs able to target Cdk13 mRNA for degradation were recently recognized during the acute myocardial infarctions supporting the idea of CDK13 as a strategic molecule for optimal heart function." (PMID 31440507, 2019).
neuroblastoma (1 paper, 2022). Neuroblastoma (NB) is the most common solid, extracranial childhood tumor. "While THZ1 appears to preferentially affect genes controlled by super-enhancers in neuroblastoma, MYCN-dependent genes in particular, there is evidence to indicate that the off-target inhibition of CDK12 and CDK13 rather than of CDK7 is responsible for the transcriptional effects of THZ1." (PMID 35681734, 2022).
pancreatic cancers (1 paper, 2016). "In addition, the abundance of CDK13 protein was found to be increased in pancreatic cancers." (PMID 26886422, 2016).
pulmonary stenosis (1 paper, 2025). "Therefore, we propose this small pulmonary trunk and large aorta is a true phenotype as a consequence of this Cdk13 deletion, resulting in pulmonary stenosis." (PMID 39556044, 2025).
Rett-like syndrome (1 paper, 2019).
situs inversus (1 paper, 2024). A congenital condition in which there is complete right-to-left reversal of the position of the major thoracic and abdominal organs (that is, they are arranged in a mirror image of the normal positioning). "Upon extensive literature review, we could not find any documented patients with CDK13-related disorder and abdominal situs inversus." (PMID 38910624, 2024).
STAR syndrome (1 paper, 2025). "As CDK13 also affects transcription through RNA polymerase II, the similarities between CHDFIDD, STAR syndrome and Ohdo syndrome may result from alterations in common cellular pathways, leading to comparable disease manifestations and facial features." (PMID 39800774, 2025).
thyroid (1 paper, 2021). "Finally, our work supports ADAR1-mediated A-to-I editing as an important pathway in cancer progression, and highlights ADAR1, CDK13 and the edited CDK13-Q103R as potential targets for the development of new treatments for thyroid and other cancer types." (PMID 34496885, 2021).
viral infection (1 paper, 2022). "Many of them, such as WDR7, INPP5E, CDK13, VAPA, NAMPT and PUM2, are known to be involved in viral infection mechanisms, whether at the point of the viral entry into the cell or during viral replication." (PMID 35563619, 2022).